IL18 (interleukin 18)
Diseases named in the same sentence as IL18 in open-access papers (continued):
Sharing a sentence is not in itself a finding about the gene and the disease.
inflammation (continued). "Chronic inflammation is the consequence of chronic activation of immune cells and an increase in secretion of proinflammatory cytokines and chemokines including IL-18, monocyte chemoattractant protein-1 (MCP-1), and macrophage inflammatory protein-1α (MIP-1α)." (PMID 30596106, 2018). "Subsequent studies confirmed that IL-18 has a role in the pathogenesis of human IBD as well as in murine intestinal inflammation." (PMID 29312281, 2017). "We employed daily injections of gp96-II peptide in two murine models of intestinal inflammation, the first resulting from five daily injections of IL-12/IL-18, the second via a single intrarectal application of TNBS (2,4,6-trinitrobenzenesulfonic acid)." (PMID 29312281, 2017). "IL-22 derived from ILC3s can induce IL-18 production in IECs and elevated IL-18 can amplify gut inflammation." (PMID 27578924, 2016). "Together, these data indicate that IL-18 represents a central mediator in the pathogenesis of intestinal inflammation and is able to play very different roles during the inflammatory process depending on the host’s inflammatory state." (PMID 23847622, 2013). "The role of caspase-1 for intrarenal IL-1β and IL-18 processing and postischemic renal inflammation was documented a decade ago, but the triggers for caspase-1 activation remained enigmatic." (PMID 22046355, 2011). "It increases interleukin-1β (IL-1β), interleukin-6 (IL-6), interleukin-8 (IL-8), and interleukin-18 (IL-18) abundance and miR-133a expression, inhibits NF-κB, and decreases phosphorylation of the ASK1/MKK7/JNK pathway in cardiomyocytes, causing cardiac inflammation and fibrosis." (PMID 40362211, 2025). "Overproduction of IL-1β and IL-18 has been reported to be involved in systemic inflammation." (PMID 38145993, 2024). "As a proinflammatory cytokine expressed in renal tubular cells, IL-18 can activate macrophages during renal inflammation and may play a crucial role in the pathogenesis of CKD." (PMID 36979422, 2023). "The activation of intracellular PRRs in cardiomyocytes leads to inflammasome activation, which converts pro-caspase-1 into the catalytically active protease that is responsible for the production of IL-1β and IL-18, subsequently triggering cardiac inflammation." (PMID 36978920, 2023). "Therefore, we studied local mRNA levels of additional cytokines that have been associated with ILC3 homeostasis, such as CXCL6, IL-1β, IL-12, IL-18, and IL-23 and/ or intestinal inflammation, including IL-1β, TGF-β, IFN-γ, and TNF-α." (PMID 28505204, 2017). "For IL-18 we observed LPS-induced increases of its levels in both age groups, with significantly greater values of this cytokine found in mesenteric tissues in control conditions as well as after development of acute peritoneal inflammation." (PMID 27875806, 2016). "IL-1β and IL-18 are proinflammatory cytokines that contribute to renal immune complex disease, but whether IL-1β and IL-18 are mediators of intrinsic glomerular inflammation is unknown." (PMID 22046355, 2011). "ASI ameliorated indomethacin‐induced intestinal inflammation in rats by inhibiting the activation of NLRP3 inflammasome and reducing the release of IL‐1β and IL‐18." (PMID 40586619, 2025). "Moreover, alirocumab not only affects lipid levels but may also offer additional cardiovascular benefits by reducing the activity of inflammatory cytokines (such as IL-18, IL-6, TNF-α) and other molecules associated with vascular inflammation (such as MMP-2, OPN, OPG)." (PMID 38017531, 2023). "IL-13, IL-1R1, IL-18, and BRP-39 knock out (KO) mice were utilized to assess the mechanism and relevance of BRP-39 in cigarette smoke- and HDM-induced airway inflammation." (PMID 21473774, 2011). "Using immunohistochemistry to detect the expression levels of IL-18 and IL-1β in tissues, it was demonstrated that ISO induced an inflammatory response and released inflammatory factors, while Gyp I intervention improved myocardial inflammation in mice with MF." (PMID 36014544, 2022).
metabolic disorders (38 papers, 2012 to 2025). "Association disease analysis linked IL‐18 to various inflammatory, autoimmune, and metabolic disorders." (PMID 39188114, 2024). "Although the NLRP3 inflammasome is essential for host defense during infections, uncontrolled activation and overproduction of IL-1β and IL-18 increase the risk of developing autoimmune and metabolic disorders." (PMID 33101288, 2020). "It is suggested that IL-18 deficiency can result in an energy unbalance, such as some sort of metabolic disorder, despite preserving renal function." (PMID 29514661, 2018). "NLRP3 inflammasome formation promotes the proximity-induced autocatalytic activation of caspase-1 and mediates the cleavage/activation and secretion/release of the pro-inflammatory cytokines IL-1β and IL-18 implicated in several metabolic disorders." (PMID 23924318, 2013). "This indicates that in patients with metabolic disorders, IL-18 plays a more significant role in the proliferation of the glandular epithelium than IL-6." (PMID 37847180, 2023). "Diverse reports have suggested that metabolic diseases are associated with chronic inflammation, in which NLRP3 inflammasome activation and IL-1β and IL-18 cytokine production have been implicated." (PMID 29151018, 2017). "Deregulated levels of IL-18 are involved in the pathogenesis of multiple disorders including inflammatory and metabolic diseases, yet relatively little is known regarding its regulation." (PMID 27149934, 2016). "The formation of an active and mature form of IL-18 depends on caspase-1 resulting from the assembly of protein complexes – inflammasomes, which are crucial for the initiation of sterile inflammation in metabolic disorders and chronic inflammatory diseases." (PMID 37847180, 2023). "Despite the significant advances in the understanding of physiological functions of IL-18 and its role in the occurrence and progression of metabolic diseases, several questions remain unanswered: What is the trigger that leads to IL-18 production by inflammasomes in metabolic diseases?" (PMID 36313762, 2022). "This indicates that caspase-1 may have a profound effect on lipid metabolism through IL-1β and IL-18 pathways, suggesting that it might play a significant role in adipose tissue as well as in metabolic diseases." (PMID 28153032, 2017). "Therefore, further studies will be required to validate these preliminary findings as well as to identify key factor(s) that can lead to upregulation of IL‐18R/IL‐18 expression in the adipose tissue in metabolic disease." (PMID 28508444, 2017). "In this study, whether there are different expressions of IL-1β, IL-18, and IL-22, which had been reported to be involved in metabolic disorder and insulin sensitivity, is interesting but yet investigated." (PMID 26681840, 2015). "Therefore, NLRP3-dependent pyroptosis and maturation of pro-inflammatory effectors (IL-1β/IL-18) induced by ROS could contribute to development of autoimmune and even metabolic diseases, such as DCM." (PMID 28790925, 2017). "It has been reported to play an important role in autoimmune and metabolic diseases by activation of CASP1 and production of IL-1β and IL-18." (PMID 36694200, 2023). "IL18 promotes BAT thermogenesis predominantly through NCC and maintains glucose sensitivity and insulin signaling through IL18r, thereby mitigating metabolic disorders." (PMID 36482059, 2022). "When activated, NLRP3 inflammasome triggers the release of pro-inflammatory interleukins (IL)-1β and IL-18, an essential step in innate immune response; however, defective checkpoints in inflammasome activation may lead to autoimmune, autoinflammatory, and metabolic disorders." (PMID 33435142, 2021). "Overweight adolescent girls with PCOS and metabolic disorders (MD+/OW) showed higher CRP, leptin, and a two-fold increase in IL-6 and IL-18 concentrations compared to the control group of healthy girls (p < 0.05 for all parameters)." (PMID 32397375, 2020).
metabolic disorders (continued). "However (4.3.2), during metabolic disorders caused by excess energy, the NLRP3 inflammasome is likely to be activated by aberrant lipid metabolites and/or high glucose levels, which subsequently results in the secretion of IL-18 as well as IL-1β, which can induce inflammatory responses." (PMID 30717382, 2019). "The group (MD+/OW) was also characterized with higher levels of CRP, leptin, MDA, IL-18, MIF (p < 0.05), when compared to overweight patients with PCOS in the absence of metabolic disorders (MD−/NW)." (PMID 32397375, 2020). "Based on this finding we can consider IL-18 as a useful novel noninvasive biomarker for differential diagnosis between obese children with and without NAFLD and prediction of possible metabolic disorders development." (PMID 29854715, 2018).
infectious disease (34 papers, 2011 to 2025). A disorder directly resulting from the presence and activity of a microbial, viral, or parasitic agent in humans. "The effect of the A-allele/AA-genotype on PCM and other infectious diseases could be explained by changes in IL-18 levels introduced by this mutant allele in the -607 position." (PMID 33117339, 2020). "Besides its role in infectious diseases, IL-18 has been implicated in the pathophysiology of various other diseases, but this falls outside the scope of this review and has been reviewed extensively in earlier reviews." (PMID 27977798, 2016). "Inflammasomes are signaling platforms that are activated in response to infectious diseases or chronic sterile inflammation and induce inflammation via triggering IL-1β and IL-18 or inducing pyroptosis via gasdermin-d (GSDMD)." (PMID 38026692, 2023). "Even though systemic IL-12+IL-18 is normally triggered in infectious diseases, their use as an antitumor treatment has been difficult to accomplish, largely due to toxicity." (PMID 36330506, 2022). "As a proinflammatory cytokine, IL-18 plays an important role in the occurrence and development of infectious diseases and tumors." (PMID 35928585, 2022). "If the role of IL-18 in inflammatory and infectious diseases is well established, recent experimental studies in mice have involved IL-18 signaling in the control of energy homeostasis, pancreatic islet immunity and liver integrity during nutritional stress." (PMID 36313762, 2022). "Similar to adjuvants including IL-12, IL-18 and IL-15, the addition of cytokine genes combined with IL-21 and IL-15 can facilitate the efficacy of potential DNA vaccines against infectious disease." (PMID 25192845, 2014). "Second, IL-18 is an important biomarker which is increased in infectious diseases and HLH." (PMID 37880605, 2023). "Interestingly, TVM cells produce large amount of IFNγ in response to IL-12+IL-18 as previously demonstrated in infectious disease murine models." (PMID 36330506, 2022). "If the roles of IL-18 in inflammatory processes and infectious diseases are well described, recent experimental studies in mice have highlighted the action of IL-18 signaling in the control of energy homeostasis, pancreatic islet immunity and liver integrity during nutritional stress." (PMID 36313762, 2022). "As the SNPs of this study had not yet been evaluated on PCM patients, we also compiled previous reports on the IL18 (-607 C/A, rs1946518 and -137 G/C, rs187238), IL12A (-504 G/T, rs2243115), and IFNGR1 (-611 A/G, rs13277474) SNPs and their association with diverse infectious diseases (respectively)." (PMID 33117339, 2020). "This demonstrates that special attention should be paid to circulating levels of free IL-18 molecules when studying the IL-18 response in infectious diseases, particularly because the ELISA kits for IL-18 detection measure the mature form of the cytokine, both free and complexed with IL-18BP." (PMID 27977798, 2016). "Previous work has implicated caspase-1 and IL-18 in this infectious disease although the pathways that led to their activation were not investigated." (PMID 22241982, 2011). "The demonstration of a BTN-independent (and thus pAg-independent) stimulatory activity of at least certain bacteria for human Vδ2 T cells, together with the essential role of IL-18 in this process, may help to better understand the role of γδ T cells in infectious diseases." (PMID 41306552, 2025). "However, some reports demonstrated that the peritoneal macrophages express IL-18 precursor and usually activate during infectious diseases because most pathogens trigger the synthesis of mature IL-1β, which, in turn, activates caspase-1 to cleave pro-IL-18 to mature IL-18, which is then secreted." (PMID 36145686, 2022).
infectious disease (continued). "Moreover, the systemic amounts of IL-12 and IL-18 we induced by hydrodynamic injections were previously assessed by our laboratory and were completely tolerated by the mice and similar to what is described for certain pathological scenarios like infectious diseases." (PMID 36330506, 2022). "Therefore, although NLRC4 is associated with infectious diseases and MAS, high levels of IL-18 seem to be only associated with the latter, and patients with refractory severe MAS have better therapeutic effects after using IL-18 blockers and gamma interferon blockers (a cytokine induced by IL-18)." (PMID 34276697, 2021). "Our findings that bipolar inhibitory neurons are regulated more strongly by IL-18 and TNF-α and subsequently lead to an overall hypoexcitability of the neural network and may explain symptoms such as dizziness or an increase in NREM sleep during infectious diseases." (PMID 27065940, 2016).
neurodegenerative disease (29 papers, 2010 to 2026). A disorder of the central nervous system characterized by gradual and progressive loss of neural tissue and neurologic function. "The NLRP3 inflammasome is a crucial signaling node in microglia that ultimately controls the maturation of pro-inflammatory interleukin (IL)-1β and IL-18 and has been linked to a multitude of neurodegenerative diseases." (PMID 31131421, 2019). "Elevated levels of proinflammatory cytokines such as IFN‐γ, IL‐1β, IL‐6, IL‐18, and TNF‐α have been shown to induce tau hyperphosphorylation and neuronal loss in AD and other neurodegenerative diseases." (PMID 38923171, 2024). "Among the various types of inflammasomes, NLRP3 inflammasome is the well-known in neurodegenerative diseases, especially in AD and PD and the activation of the NLRP3 inflammasome causes the production of IL-1β and IL-18 in microglia cells." (PMID 34922574, 2021). "Recent studies have shown that levels of IL-1β and IL-18 in the brain tissue, plasma and CSF in patients with neurodegenerative diseases, brain injury and CNS infection are elevated, suggesting that IL-1β and IL-18 are involved in neuroinflammation." (PMID 31681133, 2019). "IL-18 can increase expression at least some of these multifunctional 14-3-3 isoforms, including 14-3-3γ and -ε, which are commonly affected in neurodegenerative diseases." (PMID 28531131, 2017). "Neurodegenerative diseases are always accompanied by chronic neuroinflammation with the excessive production of IL-1β and IL-18 pro-inflammatory cytokines, which has detrimental consequences for brain structure and function." (PMID 28337127, 2017). "In neurodegenerative diseases and neuroinflammation, the accumulation of misfolded proteins, such as beta-amyloid and alpha-synuclein, can lead to inflammasome activation, resulting in the release of interleukin (IL)-1β and IL-18." (PMID 39710713, 2024). "The main aim of the present study was to discover other relevant molecules and/or mechanisms in these human cells that are regulated by IL-18 and that may have general importance in the pathogenesis of neurodegenerative diseases, including AD." (PMID 25147500, 2014). "IL-18 significantly increased antioxidative enzymes, indicative of OS, and altered levels of glycolytic α- and γ-enolase and multifunctional 14-3-3γ and -ε, commonly affected in neurodegenerative diseases." (PMID 25147500, 2014). "We hypothesized that IL-18 has a role in the development of neuropathological changes related to several neurodegenerative diseases including AD." (PMID 25147500, 2014). "Systemic inflammation might cause neuronal damage and sustain neurodegenerative diseases and behavior impairment, with the participation of pro-inflammatory cytokines, like tumor necrosis factor (TNF)-α and interleukin (IL)-18." (PMID 22642744, 2012). "These actions were both demonstrated and IL-18 was shown to promote loss of appetite, sleep and inhibition of LTP, as well as to be produced by and active in microglial cells, and to possibly contribute to neurodegenerative diseases." (PMID 20113500, 2010). "IL-18 can enhance Aβ production and the kinases Cdk5 and glycogen synthase kinase-3β (GSK-3β), which are involved in the hyperphosphorylation of tau, caspase-1 regulation as well as many other neurodegenerative diseases linked proteins, and cellular vacuolization." (PMID 28531131, 2017). "Elevated IL-1β, IL-18, and inflammasome proteins such as ASC and caspase-1 have been reported in neurodegenerative disease and TBI, often correlating with severity or outcome." (PMID 41511361, 2026). "Anti-IL18 antibodies are available as a potential pharmacological approach as well as recombinant IL18 binding protein but have not yet been investigated for neurodegenerative disease." (PMID 38483732, 2024).
neurodegenerative disease (continued). "The results showed that ChT, IL-16, IL-18, and TGF-β1 increased in ischemic cerebrovascular disease (CVD) and AD, confirming that the immune system may play an important role in the development of neurodegenerative diseases." (PMID 37270510, 2023).
neurological diseases (17 papers, 2020 to 2024). "Our findings are consistent with previous studies implicating IL-18 dysregulation in neuroinflammatory processes and neurological disorders." (PMID 39858411, 2024). "Pyroptosis involves the release of intracellular proinflammatory factors (including IL-18 and IL-1β), and pyroptosis-regulated cell death plays a key role in the pathogenesis of various neurological diseases including SCI." (PMID 34764819, 2021). "EA can effectively reduce the levels of interleukin-1β (IL-1β), interleukin-6 (IL-6), interleukin-18 (IL-18), and tumor necrosis factor-α (TNF-α), helping to inhibit the inflammatory response in a variety of neurological diseases." (PMID 33204250, 2020). "Microglia from non-neurological disease controls and individuals with ASD in both the snRNA-seq and scRNA-seq datasets expressed characteristic microglial markers such as P2RY12, CX3CR1, AIF1, CSF1R and IL18." (PMID 35739273, 2022).